RN7SL87P (RNA, 7SL, cytoplasmic 87, pseudogene)
Gene: Miscellaneous RNA gene on chromosome 5 (144,140,879 to 144,141,166, forward strand). Ensembl gene ENSG00000239390.
Homologues: Orthologues: chimpanzee Metazoa_SRP (98% identical), macaque Metazoa_SRP (80% identical), dog Metazoa_SRP (65% identical). Paralogues in human: RN7SL1 (77% identical), RN7SL2 (76% identical), RN7SL5P (76% identical), RN7SL3 (75% identical), RN7SL4P (74% identical), RN7SL712P (74% identical), RN7SL778P (73% identical), RN7SL769P (73% identical), RN7SL186P (72% identical), RN7SL230P (72% identical), RN7SL559P (72% identical), RN7SL210P (72% identical), and 700 more.